C4A (complement C4A (Chido/Rodgers blood group))
Diseases named in the same sentence as C4A in open-access papers (continued):
Sharing a sentence is not in itself a finding about the gene and the disease.
breast cancer (16 papers, 2014 to 2025). A primary or metastatic malignant neoplasm involving the breast. "Furthermore, we also found that other peptides (fragment of complement C4-A (m/z 1898.21) and breast cancer type 2 susceptibility protein (m/z 1607.84)) can be used in predicting biological age, whereas their specific mechanisms in ageing remain to be elucidated." (PMID 32501290, 2020). "Some of these proteins have been previously reported to be breast cancer related biomarkers, such as C4a, HER2, CA15-3, alpha-1-antichymotrypsin and alpha-1B-glycoprotein." (PMID 26375396, 2015). "For the five FTD-Breast cancer comorbid genes (AKT3, GFAP, C4A, VDAC1, ADCYAP1R1), we analyzed the alterations in the genetic profiles among the different subtypes of Breast cancer." (PMID 37834358, 2023).
Cirrhosis (13 papers, 2015 to 2026). A chronic disorder of the liver in which liver tissue becomes scarred and is partially replaced by regenerative nodules and fibrotic tissue resulting in loss of liver function. "In our study, increased plasma levels of C4a were independently associated to HCC development in HCV-infected alcoholic patients with cirrhosis, and showed a fair diagnostic accuracy (AUROC 0.70)." (PMID 25789864, 2015).
depression (13 papers, 2012 to 2026). "C4A, also called Complement C4A, plays a key role in the human immune system and has established links with depression and IBD." (PMID 41438618, 2025). "The median serum concentrations of C4A were 269.05μg/mL, 165.11μg/mL in depression patients, healthy controls, respectively, with significant difference between the two groups." (PMID 38895030, 2024). "The elevated C4A serum levels in depression patients in this study suggest that C4A may be a potential serum biomarker for depression." (PMID 38895030, 2024). "STRING software showed that ITIH4, C3, C4A and TUBB were involved in the pathogenesis of depression through an unknown pathway." (PMID 38895030, 2024).
fibrosis (12 papers, 2016 to 2024). the formation of excess fibrous connective tissue in an organ or tissue in a reparative or reactive process. "The systemic levels of C3a, C4a and C5a in different types of nAMD (e.g. CNV, RAP, PCV and fibrosis) or in different anti-VEGF therapy responder groups have not been investigated before, and such studies are important as different immunomechanisms may be involved in different types of nAMD." (PMID 26884800, 2016).
liver fibrosis (12 papers, 2012 to 2023). "Furthermore, in the PNALT-2 group, serum C4a levels negatively correlated with transaminase levels, but not with other biochemical tests, HCV core antigen levels, peripheral blood cell counts or serum hepatic fibrosis markers." (PMID 22614103, 2012).
type 1 diabetes (12 papers, 2006 to 2026). "Four genes encoding complement proteins (factor B, C2, C4A and C4B) are located on chromosome 6 in the human major histocompatibility complex (MHC) that also contains the type 1 diabetes associated HLA-genes." (PMID 27306948, 2016). "Kininogen/complement C3/complement C4-A were not correlated with maternal HbA1c in all three trimesters in women with type 1 diabetes." (PMID 35610262, 2022).
Alzheimer disease (11 papers, 2011 to 2025). A progressive, neurodegenerative disease characterized by loss of function and death of nerve cells in several areas of the brain leading to loss of cognitive function such as memory and language. "Six genes C4A, C4B, CXCL12, FCGR3A, IL1B, and MMP3 were identified as the most significant crosstalk genes linking chronic periodontitis and Alzheimer's disease." (PMID 33869630, 2021).
IgA nephropathy (11 papers, 2019 to 2025). "In addition, another study showed that the gene expression of C4a increased the risk of IgA nephropathy, which was also consistent with our evidence that protein C4a is associated with IgA nephropathy." (PMID 38898508, 2024). "Therefore, we hypothesize that C4A and C4B genes may influence the occurrence and development of IgA nephropathy by regulating complement activation and immune complex metabolism." (PMID 40149558, 2025).
psychosis (11 papers, 2019 to 2026). "It remains to be determined in future studies whether the observed increase in C4A protein levels is attributed to underlying biochemical alterations with considerable biological impact on the disposition to psychosis." (PMID 35532796, 2022). "We analyzed cerebrospinal fluid (CSF) levels of C4A, C4B, C1Q, along with 48 inflammation-related proteins, measured in both CSF and plasma, in 90 healthy controls and 113 patients with first-episode psychosis (FEP)." (PMID 42000733, 2026). "Our findings outline that a specific dysregulation of C4A isotype levels may exist in psychosis, at least in the very early stages of the illness, which could not be detected using methods that estimate total amount of complement C4 (i.e., C4A and C4B levels)." (PMID 35532796, 2022). "Importantly, our results indicate C4A cascade alterations in un-medicated cases with FEP, suggesting an abnormal innate immune reaction during the early course of psychosis." (PMID 35532796, 2022).
Stroke (11 papers, 2012 to 2026). Sudden impairment of blood flow to a part of the brain due to occlusion or rupture of an artery to the brain. "At 8 weeks post-stroke, the top 10 genes were Cd44 (degree = 14), Fcgr2b (degree = 13), C1qb (degree = 13), Cd74 (degree = 12), C1qc (degree = 11), Cd14 (degree = 10), C4a (degree = 10), Spp1 (degree = 10), RT1-A2 (degree = 9), and Itgb2 (degree = 9)." (PMID 31888302, 2019). "At 4 weeks post-stroke, the top 10 gene products in the PPI network were Cd44 (degree = 17), C1qb (degree = 15), Fcgr2b (degree = 14), Spp1 (degree = 12), Cd74 (degree = 12), C4a (degree = 12), C1qa (degree = 12), C3 (degree = 10), Cd14 (degree = 10), and Itgb2 (degree = 10)." (PMID 31888302, 2019).
Immunodeficiency (10 papers, 2012 to 2025). Failure of the immune system to protect the body adequately from infection, due to the absence or insufficiency of some component process or substance. "Drug (Human immunoglobulin G) targeting C4A is used in the treatment of immunodeficiencies, as well as autoimmune and inflammatory disorders." (PMID 39175755, 2024). "The study stratified ME/CFS patients into two groups based on their immunological status and presented three key findings: Reduced C4a levels in ME/CFS patients with immunodeficiencies suggested a subgroup-specific disease pattern impairing innate immunity." (PMID 38202282, 2024). "However, after stratifying ME/CFS patients based on their immune competence, we found statistically reduced C4a levels in ME/CFS patients with immunodeficiencies compared to both other test groups." (PMID 38202282, 2024).
preeclampsia (10 papers, 2016 to 2025). Preeclampsia is a hypertensive disorder of pregnancy that is characterized by new-onset hypertension with proteinuria presenting after 20 weeks of gestation, and depending on mild or severe forms may initially present with severe headache, visual disturbances, and hyperreflexia. "A low concentration of maternal plasma C4a is associated with preeclampsia and small-for-gestational age fetuses during pregnancy." (PMID 35069847, 2022). "C4a protein expression is lower in JAR cells under hypoxic conditions compared with normoxic conditions, indicating that preeclampsia is associated with low C4a and hypoxia." (PMID 35069847, 2022). "Significantly lower plasma concentrations of C4A were observed in women with severe, early-onset preeclampsia compared to those with severe, late-onset preeclampsia." (PMID 35610262, 2022).
thrombosis (9 papers, 2009 to 2024). "Here, we further show that patients with both SLE and thrombosis had the lowest mean GCNs for total C4 (3.55) and C4A (1.81), which underscores the importance of C4A deficiency as a genetic risk factor for systemic autoimmune disease." (PMID 31134052, 2019). "In another study investigating the significance of C3 and C4 in antiphospholipid syndrome, approximately, 40% lower levels of C4 (both C4A and C4B) were observed in thrombotic SLE patients with reference to thrombosis-free SLE patients." (PMID 35359932, 2022). "We also observed significantly lower GCNs of total C4 and C4A among aPL-positive patients with both SLE and thrombosis than others." (PMID 31134052, 2019). "Among the NTS subjects who were not afflicted with thrombosis and SLE, there were higher mean GCN of C4A, which would be protective against SLE; and low GCN of C4B that would lead to lower C4B protein levels and thereby reducing the risk of thrombosis." (PMID 31134052, 2019). "When the aPL subjects were segregated and compared based on both thrombosis and SLE status, it revealed that the NTS group without thrombosis and SLE had the highest mean GCNs for total C4 and C4A (3.78 and 2.12, respectively), but the lowest C4B mean GCN (1.66)." (PMID 31134052, 2019).
glaucoma (7 papers, 2011 to 2024). Increased pressure in the eyeball due to obstruction of the outflow of aqueous humor. "Interestingly, all of the identified proteins except C4a are known plasma proteins and increased expression in the AH suggests a breach in the blood aqueous barrier caused by a glaucoma drainage device." (PMID 21850163, 2011). "Furthermore, the findings from our study indicate that four additional complement proteins, C4A, C4B, F2, and C7, were significantly elevated in the African American population with glaucoma compared to those with cataracts." (PMID 37763167, 2023). "Our observations may suggest an important role of C4a in the early stages of glaucoma that warrants further investigations." (PMID 32585848, 2020). "Interestingly, C4a down-regulation has been also observed at a systemic level in humans with glaucoma (POAG or PEXG, 0.8-fold)." (PMID 32585848, 2020). "We quantified the majority of key proteins associated with classical complement pathway, such as C1q, C1s, C1r, C4a, C4b, C3, C5, C6, C7, C8a, C8b, C8g and C9, as up-regulated in glaucoma condition for both vitreous and retinal tissues when compared to the controls." (PMID 28978942, 2017). "They found a significant increase in the expression of complement proteins (C1R, C2, C4A/C4B, C5, C6, C8A, C9, CFB, CFI, and VTN) in glaucoma patients as compared to the control cataract patients." (PMID 38396986, 2024). "As a proof of concept, the use of a five-protein panel, consisting of C4a, CFH, FCN3, APOA4, and TTR predicts the transition to glaucoma disease in 78% of cases." (PMID 32585848, 2020). "Moreover, the five-protein panel, consisting of C4a, CFH, FCN3, APOA4, and TTR, predicted the transition to glaucoma in 78% of cases and correctly classified 89% of cases with advanced glaucoma in this animal model." (PMID 32585848, 2020). "As noted, the DBA/2J mice that did not develop glaucoma (DBA/2J_NG) showed similar C4a levels at 4, 10, and 14 months of age, and therefore this complement protein remains almost constant in the control group." (PMID 32585848, 2020).
melanoma (7 papers, 2016 to 2025). A malignant, usually aggressive tumor composed of atypical, neoplastic melanocytes. "Several of their findings were replicated including C4A, MICA and MICB associated with multiple cancers as well as ASIP with skin cancers (basal cell, squamous cell carcinoma and melanoma in our analysis)." (PMID 41358317, 2025).
periodontitis (7 papers, 2019 to 2025). An acute or chronic inflammatory process that affects the tissues that surround and support the teeth. "C4A encodes the classical complement factor C4, and patients with C4 deficiency are more prone to severe chronic periodontitis." (PMID 36457739, 2022). "C4B and C4A, respectively, encode the basic and acidic forms of the complement factor 4, and C4 gene deficiency has been noted to predispose the development of severe chronic periodontitis." (PMID 33869630, 2021). "The machine learning algorithms here detected several recognized periodontitis biomarkers or inflammatory factors, including C3, C4A, CRCR4, and CXCL1, confirming the algorithms’ accuracy." (PMID 36457739, 2022). "Whether C4a might mediate complement crosstalk with the coagulation and/or the endothelial barrier system is currently uncertain as is the impact of such interactions on periodontitis." (PMID 30915073, 2019). "Among these 48 crosstalk genes and the chronic periodontitis-related genes in DisGeNET, C4A, C4B, CXCL12, FCGR3A, IL1B, and MMP3 were shared and identified as the most pivotal candidate links between periodontitis and AD." (PMID 33869630, 2021). "Exploration of available transcriptomic datasets revealed C4A, C4B, CXCL12, FCGR3A, IL1B, and MMP3 as the top candidate molecular linkage genes between periodontitis and AD." (PMID 33869630, 2021).
psoriasis (7 papers, 2010 to 2024). An autoimmune condition characterized by red, well-delineated plaques with silvery scales that are usually on the extensor surfaces and scalp. "The role of C4 cleavage and C4a production as activating products in trauma significantly increased serum C4 levels in patients with atopic dermatitis and psoriasis; a decrease in serum C4 levels represents an increase in anti-inflammatory effects." (PMID 39408763, 2024). "Regarding systemic complement activation, sera, and plasma from psoriasis patients showed elevated levels of complement components, complement split products, and regulator proteins including FB, Bb, C3, C3a, C3b, C4, C4a, C4d, C5b-9, C1-INH, C4BP, FH, and FI." (PMID 29713318, 2018).
retinal degeneration (7 papers, 2017 to 2025). Degeneration of the retina. "Nevertheless, this complement component should be further studied in retinal degeneration, especially in regard to the complexity of the c4 gene locus and the association of copy number variations of the C4A gene in different disease." (PMID 28676742, 2017).
asthma (6 papers, 2013 to 2024). "Two of them measured C4 and C4a from plasma with the MS technique, and found elevated levels of C4a in immediate-phase reaction and aspirin-induced asthma groups." (PMID 38892755, 2024). "Many of the upregulated genes in nicotine-treated sperm are known to be involved in asthma pathogenesis, including L-Histidine decarboxylase (Hdc), Fc receptor-like 3 (Fcrl3), Endothelin receptor type B (Ednrb), and Complement C4A (C4a)." (PMID 35600600, 2022).
co-infection (6 papers, 2013 to 2024). "However, C4A was excluded from the salivary glands of these Ly49H+ BALB/c background mice during co-infection." (PMID 23300458, 2013). "However after co-infection with all four MCMV strains, C4A and C4B were undetectable at this site." (PMID 23300458, 2013).
malaria (6 papers, 2009 to 2024). Malaria is a serious and sometimes fatal disease caused by a parasite that commonly infects a certain type of mosquito which feeds on humans. "Taken together, these data confirmed the complement system activation observed in the proteomics data (by decreasing complement system inhibitors and increasing C4a) during malaria in pregnancy at the time of delivery." (PMID 37628675, 2023). "In a case-control study, C activation was assessed by measuring serum haemolytic activity (CH50), functional activity of each pathway and levels of C3a, C4a and C5a in children presenting at Kisumu District Hospital, western Kenya, with severe malarial anaemia (SMA) or uncomplicated malaria (UM)." (PMID 19134190, 2009).
multiple sclerosis (6 papers, 2008 to 2025). A progressive autoimmune disorder affecting the central nervous system resulting in demyelination. "Elevated C4A in CSF, a marker for disease activity in multiple sclerosis, was noted for two of the three cases, notably the same two that showed elevated sCD27 in CSF." (PMID 39304742, 2025). "Upregulation of C4A has been described in the CSF of a fulminant case of multiple sclerosis." (PMID 28326060, 2017).
nephrotic syndrome (6 papers, 2010 to 2025). A collection of symptoms that include severe edema, proteinuria, and hypoalbuminemia; it is indicative of renal dysfunction. "Additionally, DQA2, C4a, and MICB were protectively associated with both chronic glomerulonephritis and nephrotic syndrome." (PMID 38898508, 2024).
pertussis (6 papers, 2015 to 2026). A contagious bacterial respiratory infection caused by Bordetella pertussis. "The genes C1QA, C1QB, C1QC, C1S, C3, and C4A in cluster 2 were predominantly enriched in top ten pathways including Staphylococcus aureus infection, pertussis and complement and coagulation cascades." (PMID 37409113, 2023).
prostate carcinoma (6 papers, 2012 to 2025). A carcinoma that arises from epithelial cells of the prostate gland. "Apart from cellular mechanism, recent studies reported that the disruption of TGFβR3 induced the dysregulation of the complement components, including C4a and the complement factor D in breast and prostate cancer." (PMID 33805946, 2021). "Interestingly, a previous study has reported that by using a combination of proteins (complement component 4a (C4a) and protein C inhibitor), a statistically significant value for predicting prostate cancer recurrence was demonstrated in men who underwent prostatectomy." (PMID 22355332, 2012).
allergic disease (5 papers, 2022 to 2026). An immune response that occurs following re-exposure to an innocuous antigen, and that requires the presence of existing antibodies against that antigen. "The role of the C3,C4 and C5 complement components and its anaphylatoxins C3a, C4a, and C5a in the development and promotion of allergies are widely discussed in the literature." (PMID 35504938, 2022).
colorectal cancer (5 papers, 2007 to 2021). A primary or metastatic malignant neoplasm that affects the colon or rectum. "The results show that FGB and C4A may be involved in pathways which are caused by advanced adenomas and subsequently colorectal cancer." (PMID 31749922, 2019). "Most promising and meaningful modifications were observed on the surface of vitamin D-binding protein (VDBP), complement C4-A (CO4A), X-ray repair cross-complementing protein 6 (XRCC6), Plasma protease C1 inhibitor (IC1), and albumin (ALBU), which are related to colorectal cancer developing." (PMID 32660089, 2020).
coronary artery disorder (5 papers, 2016 to 2025). Narrowing of the coronary arteries due to fatty deposits inside the arterial walls. "In particular, HDL of healthy subjects was found associated with C4a, C4b, and C9, whereas HDL of patients with coronary artery disorder presented higher composition of C3 and C4 factors." (PMID 34205975, 2021). "The HDL of healthy people comprise C4a, C4b, C9, and vitronectin, while the HDL of patients with coronary artery disorder are enriched in C3 and C4." (PMID 33228032, 2020).
myositis (5 papers, 2011 to 2023). "Complement C4 or C3 protein or C4P/G, HLA-DRB1*03 and/or HLA-DRB1*15, C4A deficiency or C4A GCN range of variations were risk factors for various myositis-related autoantibodies except for MSA in general." (PMID 36171069, 2023). "The relative roles of HLA-DRB1*03 and C4A deficiency on genetic risk of IIM, and how the C4 GCN variations and complement protein levels correlated with the presence of myositis-related autoantibodies were also examined." (PMID 36171069, 2023).
pancreatic cancer (5 papers, 2010 to 2025). "A study in patients with pancreatic cancer revealed that preoperative plasma levels of nine proteins, including complement factors C1q-B, C3 and C4A correlated with the 1-year disease-free survival." (PMID 20877360, 2010).